INS (insulin)
Diseases named in the same sentence as INS in open-access papers (continued):
Sharing a sentence is not in itself a finding about the gene and the disease.
lymphedema (9 papers, 2012 to 2025). Excess fluid collection in tissues, causing swelling. "In this review, we investigate the interplay between insulin resistance and lymphatic vessel dysfunction as a novel mechanism underlying lymphedema progression." (PMID 41403736, 2025). "Human insulin was identified as the most common antigen detected by lymphedema-associated T cells." (PMID 40821816, 2025). "However, depending on the patient with respect to cancer therapy, comorbidities, among other factors, whether insulin-reactive T cell clones are a cause or consequence of lymphedema is yet to be elucidated." (PMID 40821816, 2025). "Our findings were further substantiated by in vitro studies demonstrating selective T cell activation in lymphedema in response to insulin." (PMID 40821816, 2025). "In vitro studies using human samples and a lymphedema mouse model demonstrated increased activated memory T cell responses specific to the antigen insulin compared with the control." (PMID 40821816, 2025). "Our study highlights an oligoclonal expansion of CD4+ T cells in lymphedema and supports insulin as a probable antigen driving T cell responses." (PMID 40821816, 2025). "The pathophysiology of lymphedema secondary to lymphatic injury involves lymphatic fluid stasis, lipid accumulation, and elevated insulin levels in lymph fluid." (PMID 40821816, 2025). "This, in turn, leads to increased secretion of insulin, contributing to the vicious cycle of lymphedema." (PMID 39045461, 2024). "CD4+ T cells isolated from lymphedema liposuction fluid stimulated ex vivo with a peptide pool from human insulin also demonstrated increased frequencies of antigen-activated T cells (CD4+CD45RO+CD154+) compared with autologous T cells from blood in a patient with normal BMI (*p<0.05)." (PMID 40821816, 2025). "Further, we assessed patient samples and found that memory T cells isolated from lymphedema fluid responded to stimulation with human insulin peptides ex vivo with a pronounced increase in insulin receptor expression, whereas autologous T cells from blood did not." (PMID 40821816, 2025). "The understanding of possible fat distribution-mediated effects and the molecular mechanisms that regulate different pathophysiological conditions (i.e., insulin sensitivity, chronic pain, and proinflammatory actions) in lymphedema need to be further investigated." (PMID 28956970, 2018). "How might a self-protein like insulin become antigenic in lymphedema?" (PMID 40821816, 2025). "In some cases, insulin-activated T cells may contribute to early disease, since previous studies have identified CD4+ T cells in general as important mediators of lymphedema." (PMID 40821816, 2025). "The lack of lymphedema-impact on glucose and insulin levels and related HOMA-IR index was suggested also by the result of our study." (PMID 33854130, 2021).
meningioma (9 papers, 2009 to 2025). A generally slow growing tumor attached to the dura mater. "Possible etiologic pathways linking MetS to increased risk of meningioma include increased insulin signalling and chronic low-grade inflammation present in adiposity." (PMID 27903988, 2017). "Dual blockade of mTORC1/2 and IGF1R/insulin signaling effectively reduced pAkt T308 and cell viability, supporting co-inhibition as a potential therapeutic strategy in NF2-deficient meningiomas." (PMID 41200151, 2025). "Overall the differential expression observed for other genes downstream of insulin and insulin growth factors pathways suggests a central role in the development of metabolic aggressiveness in histological benign meningioma." (PMID 23840654, 2013). "Use of sulfonylureas showed no clear association with meningioma, whereas for insulin there was the suggestion of an inverse relation, in particular, when comparing a high vs. low number of prescriptions." (PMID 28708856, 2017). "By comparison, the number of insulin prescriptions showed a statistically non-significant inverse relation to meningioma (p-value for trend = 0.147)." (PMID 28708856, 2017).
multiple system atrophy (9 papers, 2019 to 2025). Multiple system atrophy (MSA) is a neurodegenerative disorder characterized by autonomic failure (cardiovascular and/or urinary), parkinsonism, cerebellar impairment and corticospinal signs with a median survival of 6-9 years. "Studies on mouse models and patients with multiple system atrophy showed insulin resistance in oligodendrocytes and neurons of the putamen and impairment of insulin/IGF-1 signaling." (PMID 34512258, 2021). "In patients with PD and multiple system atrophy (MSA), an improvement of motor and cognitive function was found after application of intranasal insulin or GLP1-agonists." (PMID 35956417, 2022).
muscular atrophy (9 papers, 2017 to 2025). "High myostatin concentration is associated with insulin resistance, which is in turn associated with muscular atrophy, resulting in poor exercise capacity and metabolic defects." (PMID 33898958, 2021). "The potential of GmA as a therapeutic compound for skeletal muscle atrophy was compared with compound Gi8, which was previously derived from G. inodorum and shown to possess insulin mimetic activity, and compound Gi1, which is a diglycoside form of GmA." (PMID 41290519, 2025). "It has been shown that increasing the core body temperature and straining the body prevent muscular atrophy, allowing for a more natural acquisition of muscle mass, enhanced stress tolerance, higher insulin sensitivity, lower inflammation, and improved cardiovascular and circulatory functions." (PMID 36685197, 2022). "Overall, the present study provides the first evidence for the role of CMP in H2O2-induced C2C12 muscular atrophy cells, and the underlying mechanism may be associated with activating the IRS-1/Akt/S6K pathway to promote protein synthesis by reducing insulin resistance and mitochondrial dysfunction." (PMID 38397848, 2024). "Accumulating evidence reveals that MOTS-c improves insulin sensitivity by modulating glucose and fatty acid metabolism 28, 29, transmits signals from the mitochondria to the nucleus 30, alters T-cell activation 31, ameliorates skeletal muscle atrophy 32, and increases physical activity." (PMID 39267782, 2024).
muscular dystrophies (9 papers, 2007 to 2024). "Moreover, expression of caveolin 3, a specific muscular marker of caveolae that is altered in other forms of muscular dystrophies and is required for insulin-stimulated glucose uptake, was also normal in cardiac and skeletal muscles from dmpk−/− mice." (PMID 17987120, 2007).
pregnancy-induced hypertension (9 papers, 2012 to 2025). "Evidence supports the use of oral antidiabetic drugs in China, particularly metformin alone or in combination with insulin to reduce the risk of adverse maternal and neonatal outcomes, including pregnancy induced hypertension, neonatal hypo glycemia, and the need for NICU admission." (PMID 28583101, 2017). "Pregnancy-induced hypertension was included as an outcome between metformin and insulin by 3 studies which involved 606 GDM patients." (PMID 31781670, 2019). "Women who had developed AGT were 3.9 times more likely to have had pregnancy-induced hypertension (PIH) during their index pregnancy, 2.8 times more likely to have required insulin during that pregnancy, and had higher glucose results at each time-point during the pregnancy glucose tolerance test." (PMID 22577574, 2012).
pulmonary embolism (9 papers, 2012 to 2025). The obstruction of the pulmonary artery or one of its branches by an embolus, sometimes associated with infarction of the lung. "To determine if home insulin use is associated with an increased mortality, we conducted a cox regression analysis that included many variables (age, race, gender, AKI, BMI, pulmonary embolism, intubation, medical inpatient treatment and insulin use at home)." (PMID 35725489, 2022). "Five adverse events (hernia, accident resulting in back pain, abdominal pain, increased fasted insulin level, rotator cuff injury) and one serious adverse event (pulmonary embolism) were reported throughout the trial duration." (PMID 33483790, 2021). "As might be expected, overweight and obese patients were more often mechanically ventilated, treated with insulin, and more likely to develop wound and skin infections as well as pulmonary embolism (P < 0.001 for each)." (PMID 23249446, 2012).
Renal cyst (9 papers, 2015 to 2025). A fluid filled sac in the kidney. "PMM2 mutation leading to abnormal glycosylation and causing cystic kidneys and the alteration of insulin secretion is the most likely pathogenesis of this clinical spectrum." (PMID 36412659, 2022). "Many patients with MODY5 have impaired insulin secretory responses to glucose and show progressive loss in basal insulin secretion, although they have various other abnormalities such as renal cysts, renal impairment, and genital malformation." (PMID 26329304, 2015). "These mechanistic categories result in a broad clinical spectrum ranging from relatively stable blood glucose levels to progressive deterioration in insulin secretion and extra-pancreatic features such as macrosomia, renal cysts, and azoospermia." (PMID 41020216, 2025). "Notably, the proportion of patients with renal cysts using insulin was lower." (PMID 33384617, 2020).
rheumatic diseases (9 papers, 2012 to 2025). "Several pharmacologic treatments for rheumatic diseases have been associated with improvements in insulin and glucose metabolism." (PMID 22676348, 2012). "In rheumatic disease patients, systemic inflammation appears to act directly on insulin and glucose metabolism through elevated levels of TNFα and IL-6." (PMID 22676348, 2012). "With HCQ's benefit as a disease-modifying antirheumatic drug, if it also improves insulin sensitivity in persons with rheumatic disease, it may be beneficial to maintain HCQ use in the rheumatic disease population." (PMID 22676348, 2012). "Chloroquine, a long standing treatment in rheumatic diseases, can reduce hepatic cholesterol synthesis and increase LDL receptor numbers on fibroblasts and enhances insulin secretion and sensitivity." (PMID 23968456, 2013).
septic shock (9 papers, 2008 to 2025). Shock caused by infection; frequently caused by gram negative bacteria, although some cases have been caused by other bacteria, viruses, fungi, and protozoa; characterized by fever, chills, tachycardia, tachypnea, and hypotension. "All septic shock patients were put on vasopressor support, 93% were on insulin therapy at study inclusion, and four patients were treated with intravenous immunoglobulin adjunctive therapy." (PMID 24350220, 2013). "Indeed, patients with septic shock have increased insulin resistance, as also suggested by the other metrics of blood glucose control in our study." (PMID 26525053, 2015).
substance abuse (9 papers, 2016 to 2025). The use of a drug for a reason other than which it was intended or in a manner or in quantities other than directed. "Modifiable hypoglycemic risk factors include the type of insulin treatment and doses, physical activity, diet and alcohol habits, and drug use or substance abuse." (PMID 38894740, 2024). "Several risk factors are, however, modifiable, for example the type of insulin treatment and insulin doses, physical activity, dietary habits, drug use or substance abuse, and others." (PMID 38894740, 2024). "In this regard, substance abuse may contribute to the non compliance with diabetic medication including insulin." (PMID 30501025, 2018).
Thiamine deficiency (9 papers, 2012 to 2022). Thiamine deficiency is a condition that occurs due to not enough thiamine (vitamin B1). "Thiamine is a co-factor for three critical enzymes for glucose metabolism, and thiamine deficiency results in an impairment of production and secretion of insulin, resulting in a reduction of glucose utilization." (PMID 35818085, 2022). "Thiamine deficiency impairs the synthesis and secretion of insulin due to decreased glucose oxidation; on the other hand, insulin deficiency can aggravate thiamine deficiency, which is also strongly associated with pathophysiological resistance in the body." (PMID 35725834, 2022). "Numerous studies have shown that thiamine deficiency in diabetic rats reduces glucose oxidation and insulin secretion, which is modified by thiamine administration." (PMID 35725834, 2022). "Thiamine is essential for insulin synthesis and secretion; thiamine deficiency in diabetic conditions affects insulin synthesis and secretion, serum insulin levels, and glucose transporters." (PMID 35725834, 2022). "Thiamine deficiency negatively impacts insulin regulation, as the pancreatic islet cells from thiamine deficient rats show impaired insulin secretion." (PMID 25878670, 2015). "The reciprocal association between insulin and thiamine could somehow answer the questions: 1) thiamine increases insulin sensitivity; 2) thiamine deficiency leads to severe dysfunction in insulin synthesis and secretion." (PMID 32933220, 2020). "This may suggest that in case of thiamine deficiency, there are other factors, besides insulin, affecting metabolism of sugars and fats." (PMID 31259440, 2019). "Thiamine deficiency exhibits slight effect on insulin level in serum." (PMID 31259440, 2019). "Thiamine deficiency was shown to impair the insulin synthesis and secretion." (PMID 23065486, 2012).
toxoplasmosis (9 papers, 2013 to 2025). A parasitic disease contracted by the ingestion or fetal transmission of toxoplasma gondii. "For subtype c5, 181 DEGs (51 up-regulated and 130 down-regulated) were detected and were enriched in Rig-I-like receptor signaling pathway, FoxO signaling pathway, autophagy-animal, insulin signaling pathway, toxoplasmosis, and focal adhesion, and so on." (PMID 32680494, 2020). "Four additional pathways (“Signaling pathways regulating pluripotency of stem cells”, “Insulin signaling pathway”, “Toxoplasmosis” and “Pathways in cancer”) were enriched in common between HBE cells, airway tissue, and either A549 or BEAS-2B cells." (PMID 30704470, 2019).
ulcerative colitis (9 papers, 2014 to 2025). An inflammatory bowel disease involving the mucosal surface of the large intestine and rectum. "Additionally, the findings of the study suggest that patients with acute severe ulcerative colitis should be closely monitored for insulin resistance." (PMID 39605944, 2024).
Ventricular arrhythmia (9 papers, 2014 to 2024). "It was believed that the simultaneous administration of potassium and insulin reduces the risk of ventricular arrhythmias, and insulin facilitates the transport of potassium into the cell." (PMID 35629267, 2022). "Prolongation of the QTc interval, especially in diabetic patients using insulin, can cause fatal ventricular arrhythmias." (PMID 33898141, 2021). "Whilst the KATP channel activators have been used to increase insulin release, they have the potential to cause life-threatening ventricular arrhythmias, especially in a subset of patients with ischaemic complications." (PMID 27642609, 2016). "The patient may have died from a ventricular arrhythmia, secondary to occult Brugada syndrome, triggered by a full stomach and insulin." (PMID 24715918, 2014).
viral myocarditis (9 papers, 2018 to 2024). Myocarditis that is caused by an infection with a viral agent. "At 24 hpi, 13 DEmRNAs (e.g. gnas, itgal) were significantly enriched in five pathways, including insulin secretion, viral myocarditis, salivary secretion, vascular smooth muscle contraction and thyroid hormone synthesis." (PMID 36991462, 2023). "gnas and itgal were enriched in the insulin secretion pathway and viral myocarditis pathway, respectively, at 24 hpi." (PMID 36991462, 2023).
Adult onset (8 papers, 2009 to 2023). Onset of disease manifestations in adulthood, defined here as at the age of 16 years or later. "Moreover, this present cohort probably excludes patients with the more aggressive form of adult-onset autoimmune diabetes, as we have excluded patients on insulin therapy in order to estimate IAA." (PMID 26239144, 2015).
autism spectrum disorder (8 papers, 2008 to 2025). A spectrum of developmental disorders that includes autism, and Asperger syndrome. "Insulin and oxytocin have been delivered via intranasal and they have been evaluated in clinical trials for treating autism spectrum disorder (ASD) and AD." (PMID 39118806, 2024). "Increased insulin/IGF levels and increased PI3K activity are also implicated in autism spectrum disorders." (PMID 19043547, 2008). "One experimental model particularly responsive to the KD is the BTBRT+tf/j (BTBR) mouse, which displays phenotypic characteristics of autism spectrum disorder (ASD) and insulin resistance." (PMID 28082920, 2016). "However, there are some limitations as insulin pumps are still not particularly accessible to visually impaired individuals, some people with autism spectrum disorder may struggle with the additional devices due to sensory issues and inserting devices with limited dexterity can be difficult." (PMID 40231429, 2025).
bacteremia (8 papers, 2012 to 2023). "On the other hand, high levels of LPS can lead to increased intestinal permeability, resulting in bacteremia and impairing insulin signaling pathways." (PMID 37834439, 2023).
Chagas disease (8 papers, 2015 to 2025). A parasitic infection caused by Trypanosoma cruzi. "Pathways such as TNF signaling, Yersinia infection, insulin resistance, proximal tubule bicarbonate reclamation, osteoclast differentiation, Chagas disease, and the sphingolipid signaling pathway were associated with the decreased DE genes." (PMID 39524487, 2024). "Patients with chronic indeterminate Chagas disease were more likely to be insulin resistant (as reflected by higher fasting insulin levels and greater HOMA-IR score) compared to subjects who were seronegative for T. cruzi infection." (PMID 31374101, 2019). "With regard to others metabolic parameters, insulin, in the majority of studies, demonstrate a reduction of its levels or a compromise of its function in Chagas’ disease patients." (PMID 26147101, 2015). "Because pancreatic secretion of insulin relies on parasympathetic neuronal inputs, parasympathetic denervation may contribute to the diminished insulin secretion in Chagas disease." (PMID 29216326, 2017). "Presence of chronic indeterminate Chagas disease was significantly associated with increasing cf-PWV values (β coefficient: 1.31, 95% coefficient interval 0.44 to 2.18, p = 0.005), even after adjustment for age, sex, heart rate, systolic blood pressure and insulin resistance." (PMID 31374101, 2019).
congenital malformations (8 papers, 2013 to 2025). "The metformin group had a lower risk of primary cesarean section (aOR = 0.57; 95% CI, 0.40–0.82) and congenital malformations (aOR, 0.51; 95% CI; 0.27–0.94) and similar risk for the other outcomes as compared with the insulin group." (PMID 32887578, 2020). "The metformin group had a lower risk of primary cesarean section (aOR, 0.57; 95% CI, 0.40–0.82; p = 0.002) and congenital malformations (aOR, 0.51; 95% CI, 0.27–0.94; p = 0.032) compared with the insulin group." (PMID 32887578, 2020). "The metformin group had lower risks of primary cesarean section (aOR, 0.50; 95% CI, 0.30–0.83; p = 0.008) and congenital malformations (aOR, 0.40; 95% CI, 0.17–0.93; p = 0.033) than did the insulin group." (PMID 32887578, 2020). "However, none of these studies were sufficiently large to accurately evaluate the incidence of events such as congenital malformations and perinatal/neonatal mortality in patients receiving insulin during pregnancy." (PMID 28100192, 2017). "Based on a review of the Sanofi global pharmacovigilance database combined with a comprehensive literature review, the available evidence does not suggest a causal association between insulin glulisine and an increased risk of pregnancy complications or congenital malformations." (PMID 29632561, 2015).